RNU6-1017P (RNA, U6 small nuclear 1017, pseudogene)
Gene: Small nuclear RNA gene on chromosome 12 (131,815,263 to 131,815,368, reverse strand). Ensembl gene ENSG00000200483.
Homologues: Orthologues: chimpanzee U6 (100% identical), macaque U6 (94% identical). Paralogues in human: RNU6-25P (84% identical), RNU6-35P (84% identical), RNU6-39P (84% identical), RNU6-1 (83% identical), RNU6-1031P (83% identical), RNU6-1181P (83% identical), RNU6-1316P (83% identical), RNU6-2 (83% identical), RNU6-29P (83% identical), RNU6-36P (83% identical), RNU6-393P (83% identical), RNU6-3P (83% identical), and 1284 more.